TXN (thioredoxin)
Diseases named in the same sentence as TXN in open-access papers (continued):
Sharing a sentence is not in itself a finding about the gene and the disease.
Sepsis (continued). "For instance, the high expression of TXN in CD16+ monocytes may affect the progression of sepsis by regulating the release of pro-inflammatory cytokines or the ferroptosis pathway, while the absence of DPP4 expression in memory CD4+ T cells may exacerbate immune suppression." (PMID 40124361, 2025). "Moreover, the expression of S100A9, NLRC4 and TXN were significantly higher in sepsis group." (PMID 40028203, 2025). "Severity of sepsis: The expression of TXN may be influenced by the severity of sepsis." (PMID 40124361, 2025). "In addition, we intend to combine in vitro cell models and animal experiments to further investigate the functions of DPP4 and TXN in pathways such as immune regulation and oxidative stress in order to gain a comprehensive understanding of their roles in sepsis." (PMID 40124361, 2025). "Group B Strep sepsis was significantly associated with multiple cell clusters, including C8_DC, C9_STOM, C10_ULK1, C12_mix, C13_UBE2Z, and C16_B, and its signature genes, including CKAP4, CPEB4, TSPO, and TXN, were significantly upregulated in multiple relevant clusters." (PMID 37919720, 2023). "Specifically, TXN was upregulated in the sepsis group, while DPP4 was elevated in the control group, positioning TXN and DPP4 as potential biomarkers." (PMID 40124361, 2025). "The results showed that the expression of IRAK3, S100A9, TXN and GSTO1 in the sepsis group was increased, while the expression of NFATC2 in the sepsis group was decreased (P < 0.05)." (PMID 40108736, 2025). "In conclusion, this research proposed three programmed cell death related genes (NLRC4, TXN, S100A9) as practical biomarkers for sepsis patients." (PMID 40028203, 2025). "The proportion of neutrophils exhibited a significant negative correlation with the expression of VDAC1, HSPA8, SOD1, HSPA9 and TXN, and a significant positive correlation with SNCA expression in sepsis-induced ALI." (PMID 40694561, 2025). "ROC curve analysis demonstrated AUC values >0.7 for TXN and DPP4 in both the training and validation sets, indicating their potential to effectively distinguish patients with sepsis." (PMID 40124361, 2025). "The logistic regression algorithm identified 8 genes (VDAC1, HSPA8, SOD1, HSPA9, TXN, NDUFS3, HSP90AB1, SNCA), among which 6 genes were closely correlated with the onset of sepsis-induced ALI (p < 0.05)." (PMID 40694561, 2025). "The machine learning algorithm screened three PCD-related genes, NLRC4, TXN and S100A9, as potential biomarkers for sepsis." (PMID 40028203, 2025). "The merged dataset (GSE57065 and GSE65682) revealed that all five genes (CD82, MAPK14, NEDD4, TXN, and WIPI1) were significantly upregulated in the sepsis group compared with the control group." (PMID 40299574, 2025). "The association analysis illustrated notable relationships between four ERRGs (including SET, LPIN1, TXN, and CD74) and sepsis." (PMID 37346041, 2023). "Based on the expression profile of SET, LPIN1, TXN, and CD74, two molecular subgroups of sepsis were obtained with K = 2, with 375 samples in cluster A and 385 samples in cluster B." (PMID 37346041, 2023). "For example, TXN and MAPK14 are expressed predominantly in monocytes, whereas WIPI1, CD82, and NEDD4 exhibit variable expression in T and B cells, highlighting the diversity and composition of immune populations during sepsis." (PMID 40299574, 2025). "We screened a signature featuring three programmed cell death related genes (NLRC4, TXN and S100A9) and found that it could predict the occurrence of sepsis." (PMID 40028203, 2025). "In order to verify the validity of the diagnostic marker genes, a KS test was performed on the GSE69063 dataset for these five genes, and the results showed that IRAK3, S100A9, TXN and GSTO1 were up-regulated in the sepsis group, while NFATC2 was down-regulated." (PMID 40108736, 2025). "Finally, we analyzed the expression of VDAC1, HSPA8, SOD1, HSPA9, TXN, and SNCA in sepsis-induced ALI in the meta-GEO cohort." (PMID 40694561, 2025).
Sepsis (continued). "This study is the first to report a significant negative correlation between DPP4 and TXN in sepsis (r = −0.43, p < 0.05)." (PMID 40124361, 2025). "In addition, a nomogram model was developed to explore the diagnostic effectiveness of the expression profiles of SET, LPIN1, TXN, and CD74 for sepsis in both cohorts." (PMID 37346041, 2023). "Taken together, diclofenac, flurbiprofen, and N-acetyl-L-cysteine may regulate ferroptosis and cellular-senescence-related pathways through specific binding to MAPK14, TXN, and NEDD4, thus providing potential pharmacological intervention strategies for sepsis treatment." (PMID 40299574, 2025). "Finally, GWAS data were relatively limited and MR Analysis could not be performed to assess whether there is a nonlinear relationship between sepsis and S100A9, TXN and GSTO1 levels." (PMID 40108736, 2025).
colorectal cancer (10 papers, 2005 to 2025). A primary or metastatic malignant neoplasm that affects the colon or rectum. "Another study conducted in patients with HCC and liver metastases from colorectal carcinoma investigated the expression levels of thioredoxin and glutaredoxin proteins belonging to the thiol oxidoreductase family." (PMID 41393733, 2025). "We used xenografts derived from colorectal carcinoma patients to investigate the pharmacological inhibition of glutathione and thioredoxin systems." (PMID 27485632, 2016). "Preliminary immunohistochemical studies suggested that in normal human colon thioredoxin is found in the dividing crypt cells, while in colorectal cancer thioredoxin is overexpressed in cancer cells." (PMID 15655539, 2005). "TXN is overexpressed in many human cancers, and high levels appear to be related to decreased patient survival, while increased transcript levels have been found in primary human lung and colorectal cancers." (PMID 32756515, 2020). "Increased expression of thioredoxin in human colorectal cancer is associated with decreased patient survival, whereas absence of thioredoxin expression in nonsmall-cell lung carcinoma is associated with a better outcome." (PMID 20584310, 2010). "Colorectal cancer tissues have also been shown to overexpress thioredoxin and hence thioredoxin could be an important therapeutic target for colon cancer." (PMID 15655539, 2005). "A potential thioredoxin inhibitor such as AW464 that targets both the tumour and endothelial cell represents an effective therapy for colorectal cancer." (PMID 15655539, 2005).
rheumatoid arthritis (10 papers, 2011 to 2025). A chronic, systemic autoimmune disorder characterized by inflammation in the synovial membranes and articular surfaces. "The expression of thioredoxin-1 (TXN1) was upregulated in both osteoarthritis and rheumatoid arthritis tissues, and TXN1 is widely involved in redox reactions in cells." (PMID 35433668, 2022). "It has been shown that TRPC5 and TRPC1 are expressed in secretory fibroblast-like synoviocytes from patients with rheumatoid arthritis, whose extracellular concentration of thioredoxin is high." (PMID 33801681, 2021). "Conversely, a recent study showed that HMGB1 is maintained in a reduced state, owing to the activity of the thioredoxin antioxidant system, in monocytes from patients with active rheumatoid arthritis." (PMID 32670275, 2020). "In the present study, we investigated the associations of two antioxidant defence proteins—lactoferrin and thioredoxin—with fibrinogen and other acute-phase proteins, such as ferritin and C-reactive protein (CRP), in patients with rheumatoid arthritis." (PMID 40943137, 2025). "For rheumatoid arthritis, systemic lupus erythematosus, ankylosing spondylitis and osteoarthritis diseases, those common factors include TNFSF10, CX3CR1, LY96, TLR5, TXN, TIA1, PRKCH, and PRF1." (PMID 26352601, 2015). "In conclusion, this study is the first to demonstrate that serum lactoferrin and thioredoxin levels are positively correlated with fibrinogen, but not with other acute-phase proteins such as ferritin and C-reactive protein (CRP) in patients with rheumatoid arthritis." (PMID 40943137, 2025).
hepatocellular carcinoma (9 papers, 2015 to 2025). A malignant tumor that arises from hepatocytes. "TXNRD1 is upregulated in many human malignancies, and inhibition of the TXN pathway causes hepatoma cell death." (PMID 30619751, 2018). "Thioredoxin expression levels were examined in HBV-associated HCC tissues and human hepatocellular carcinoma cells (HepG2) to investigate the relationship between intracellular ROS regulation and metastasis." (PMID 41393733, 2025). "Thioredoxin reductase 1 (TXNRD1) is a member of the thioredoxin system, regulating hepatocellular carcinoma, epilepsy, osteosarcoma." (PMID 37621558, 2023). "For example, a study of hepatocellular carcinoma (HepG2) cells reported that HIF-1α upregulated the thioredoxin (TXN), a common anti-oxidant, and thereby reduced oxidative stress." (PMID 36105189, 2022). "Increased expression of TXN in hepatocellular carcinoma cells correlated with increased HIF-2α stability by PTMs." (PMID 35267567, 2022). "However, the role of thioredoxin proteins in hepatocellular carcinoma (HCC) remains largely unknown." (PMID 30382079, 2018). "Here we found that serum levels of thioredoxin were increased in patients with hepatocellular carcinoma (HCC)." (PMID 25871387, 2015). "In hepatocellular carcinoma, genomic modifications were mainly detected in the KEAP1 gene and in urothelial bladder carcinoma a probable link with NRF2 and thioredoxin signaling was observed." (PMID 32443774, 2020). "Notably, TXN is shown to be induced by hypoxia, specifically HIF-1α, in hepatocellular carcinoma (HepG2) cells." (PMID 35267567, 2022).
oral cancer (9 papers, 2010 to 2024). "NRF2, TXN, and HMOX1 genes were downregulated by fucoidan treatment in oral cancer, causing oxidative stress." (PMID 36139851, 2022). "In the present study, EANT generates oxidative stress, which is accompanied by mRNA overexpression for antioxidant genes (NFE2L2, CAT, HMOX1, and TXN) in oral cancer cells." (PMID 34575651, 2021). "Increased secretion of thioredoxin had been previously demonstrated in the saliva of patients with oral cancer." (PMID 21151451, 2010). "Pomegranate extract also downregulates NFE2L2, TXN, CAT, SOD1, and HMOX1 gene expressions in oral cancer cells and induces oxidative stress." (PMID 36139851, 2022). "Accordingly, the antioxidant signaling gene expression for mRNA, including NFE2L2, GCLC, TXN, CAT, SOD1, HMOX1, and NQO1, was examined for POMx-incubated oral cancer cells." (PMID 34356350, 2021). "Similar to the present study, the mRNA expressions for several antioxidant genes (NFE2L2, GCLC, TXN, CAT, SOD1, HMOX1, and NQO1) were downregulated at 24 h POMx for three oral cancer cell lines." (PMID 34356350, 2021). "In response to oxidative stresses, the mRNA for antioxidant signaling, such as nuclear factor erythroid 2-like 2 (NFE2L2), catalase (CAT), heme oxygenase 1 (HMOX1), and thioredoxin (TXN), are overexpressed in oral cancer cells." (PMID 34575651, 2021). "A study showed that a combination of several salivary biomarkers (proteins such as thioredoxin and IL-8 and mRNAs such as SAT, ODZ, IL-8, and IL-1b) are able to detect oral cancer with high specificity and sensitivity." (PMID 34359370, 2021). "In the current study, antioxidant gene expressions (NFE2L2, SOD1, TXN, GSR, CAT, and GPX1) in oral cancer Ca9-22 and CAL 27 cells were highly downregulated by UVC/sinularin combined treatments compared to the separate treatments." (PMID 34070049, 2021). "Accordingly, the gene expressions of antioxidant genes such as NFE2L2, SOD1, TXN, GSR, CAT, and GPX1 were evaluated by qRT-PCR following UVC and/or sinularin treatments in oral cancer cells (Ca9-22 and CAL 27)." (PMID 34070049, 2021). "Similarly, pomegranate extract (POMx) downregulates mRNA expressions of the NRF2, TXN, and HMOX1 genes to induce oxidative stress in oral cancer Ca9-22 cells." (PMID 35624705, 2022). "Antioxidant genes (NRF2, TXN, and HMOX1) were downregulated in fucoidan-treated oral cancer cells but not in non-malignant oral cells." (PMID 35624705, 2022). "These oxidative stress effects were attributed to the downregulation of antioxidant signaling genes (NRF2, TXN, and HMOX1) in oral cancer cells rather than S–G cells." (PMID 35624705, 2022).
viral infection (9 papers, 2015 to 2022). "This supports suggestions that GSH can inhibit viral infections and that viral infections induce the appearance of glutathionylated thioredoxin and PRDX family." (PMID 35937690, 2022). "A series of reports documented that increased production of thioredoxin h was triggered by accumulation of ROS and misfolded proteins in ROS homeostasis in defense against fungal and viral infections and abiotic stress." (PMID 33747013, 2021). "For example, this was the case for class 3 lipases, peptidoglycan peptidase and thioredoxin, indicating their role in the final steps of the replicative cycle, probably in regulation of host responses to viral infection and production of new progeny." (PMID 32390970, 2020). "We have little information about the definite role of the thioredoxin antioxidant complex system during viral infection, particularly during human T-cell lymphotropic virus type 1 (HTLV-1) infection and the HTLV-1-associated myelopathy/tropical spastic paraparesis (HAM/TSP) state." (PMID 32974569, 2020). "The thioredoxin system has been demonstrated to play a key role in modulating redox signaling pathways and can be induced by a wide variety of stress conditions, such as oxidative stress, ultraviolet irradiation, γ-rays, hypoxia, lipopolysaccharide, and viral infections." (PMID 29599892, 2018).
Alzheimer disease (8 papers, 2008 to 2023). A progressive, neurodegenerative disease characterized by loss of function and death of nerve cells in several areas of the brain leading to loss of cognitive function such as memory and language. "Therefore, this study investigates the therapeutic role of SY5 as the prodrug of SY6 in the thioredoxin system in the brain of a mouse model of Alzheimer’s disease." (PMID 34500775, 2021). "However, Alzheimer’s disease (AD) is characterized by hypoxia and oxidative damage and - similar to our findings–increased TXNRD levels, but decreased thioredoxin levels were found in AD brains." (PMID 36589435, 2022).
pancreatic cancer (8 papers, 2007 to 2025). "Inhibiting TXN expression has been shown to significantly decrease the proliferation, apoptosis, migration, and invasion of pancreatic cancer cells." (PMID 39859536, 2025). "Data show that targeting of the thioredoxin system with Au inhibits thioredoxin reductase activity and sensitizes pancreatic cancer cells to P-AscH−-generated H2O2." (PMID 35624835, 2022). "Due to its significant role in ROS regulation, the thioredoxin (Trx) system has been an attractive therapeutic target for a number of cancers including pancreatic cancer, squamous cell carcinoma (SCC), breast cancer and chronic myeloid leukemia." (PMID 26573231, 2016). "A reactive oxygen species (ROS) sensor thioredoxin binding protein (TXNIP) and thioredoxin (TXN) were evaluated in pancreatic cancer cells (Panc0403, MiaPaCa2) following treatment with either HNA or 3ETH." (PMID 24952679, 2014). "In fact, different studies have isolated different molecules, like KLF11, retinoblastoma, thioredoxin, which are involved in Smad7 dependent aggressiveness of pancreatic cancer." (PMID 22195733, 2011). "Based on these findings, it was hypothesized that inhibition of thioredoxin reductase by Au would disrupt the thioredoxin-dependent hydroperoxide scavenging system and sensitize pancreatic cancer cells to P-AscH− treatment." (PMID 35624835, 2022). "Interestingly, thioredoxin is identified as a gene whose basal expression is increased in pancreatic cancer cells in which Smad7 is commonly overexpressed." (PMID 17224927, 2007). "Future studies are necessary to investigate whether or not thioredoxin is downregulated in gemcitabine-resistant pancreatic cancer cells." (PMID 17224927, 2007).
endothelial dysfunction (7 papers, 2011 to 2024). In vascular diseases, endothelial dysfunction is a systemic pathological state of the endothelium (the inner lining of blood vessels) and can be broadly defined as an imbalance between vasodilating and vasoconstricting substances produced by (or acting on) the endothelium. "Endothelial cells have developed a sophisticated antioxidant defense system to prevent intracellular ROS accumulation and endothelial dysfunction, including glutathione (GSH), SOD, catalase, peroxiredoxins (Prx), and thioredoxin (Trx)." (PMID 34575985, 2021). "Moreover, SIRT1 deacetylates FoxO proteins and thus stimulates FoxO-dependent anti-oxidative enzymes, such as catalase (CAT), manganese superoxide dismutase (MnSOD), and thioredoxin (TRX), eliminating ROS from endothelial cells and thus preventing endothelial dysfunction." (PMID 38003402, 2023).
glioblastoma (7 papers, 2019 to 2025). The most malignant astrocytic tumor (WHO grade IV). "Glioblastoma stem cells (GSCs) increase thioredoxin (Trx) and glutathione (GSH) antioxidant systems as survival redox-adaptive mechanisms to maintain ROS below the cytotoxic threshold." (PMID 39456455, 2024). "This work aimed to evaluate the cytotoxicity of EtHg and TmHg in mouse glioblastoma cells as a consequence of disruption in the thioredoxin system." (PMID 35813817, 2022). "On the other hand, SH-SY5Y cells have very low levels of the redox protein thioredoxin that together with glutathione redox cycle represents the major cellular redox buffer, acts as a growth factor and is found to be overexpressed in many human primary cancers including glioblastoma cells." (PMID 31500197, 2019). "Recently, a protective effect of SELM on non-alcoholic fatty liver disease, cytotoxic effect of recombinant SELM on human glioblastoma cells, and SELM’s promotion of leptin signaling and thioredoxin activity have been reported." (PMID 38890329, 2024). "Meanwhile, various subsets of tumor cells, such a glioblastoma stem cells (GSC) or the cells in tumor microenvironment (TME), demonstrate adaptive mechanisms to excessive ROS production by developing effective antioxidant systems such as glutathione- and thioredoxin-dependent." (PMID 40076706, 2025).
glioma (7 papers, 2013 to 2025). A benign or malignant brain and spinal cord tumor that arises from glial cells (astrocytes, oligodendrocytes, ependymal cells). "Adding S100B to cells containing either wild type Thioredoxin or mutated TSc induces normal RAGE signaling in both C6 glioma and VSMC cells." (PMID 23785412, 2013). "Taken together, metabolic modelling accurately captured pan-glioma single vulnerabilities, such as thioredoxin detoxification and nucleotide interconversion." (PMID 38701414, 2024). "In conclusion, investigated TrxR inhibitors are effective anticancer compounds, acting through inhibition of the thioredoxin system and perturbation of antioxidative defense systems of glioma cells." (PMID 33134322, 2020). "Thioredoxin system is also important for supporting chemoresistance in gliomas." (PMID 40076706, 2025). "The thioredoxin and glutathione systems are the key cellular redox systems involved in gliomas." (PMID 33329553, 2020). "Therefore, this study evaluated the effects of thimerosal (TmHg) and its metabolite ethylmercury (EtHg) over the mouse glioma cell line (GL261), namely, the inhibition of the thioredoxin system and the occurrence of oxidative cellular stress." (PMID 35813817, 2022).